ABCC10 (ATP binding cassette subfamily C member 10)
Diseases named in the same sentence as ABCC10 in open-access papers (continued):
Sharing a sentence is not in itself a finding about the gene and the disease.
cancer (25 papers, 2013 to 2026). A tumor composed of atypical neoplastic, often pleomorphic cells that invade other tissues. "Moreover, previous studies have reported that paclitaxel is an excellent P-glycoprotein (ABCB1) substrate, and that multidrug resistance-associated protein 7 (MRP7/ABCC10) expression is a predictive biomarker for the resistance to paclitaxel in various types of cancer cells." (PMID 35141332, 2022). "As expected, compared to their respective control parental cancer cells, the viability of both ABCC10-knockout and ABCC10-knockdown cells was significantly reduced in response to RT." (PMID 40770563, 2026). "Conversely, in ABCC10-knockout or ABCC10-knockdown cancer cells, the upregulation of pTBK1, pIRF3, and IFNB1 was further amplified in the presence of both exogenous and endogenous cGAMP." (PMID 40770563, 2026). "PicoGreen staining revealed higher fluorescence intensity around the nucleus in RT-treated ABCC10-knockout cancer cells compared to other groups, indicating elevated cytoplasmic DNA levels." (PMID 40770563, 2026). "By contrast, ABCC10-overexpressing cancer cells displayed lower green fluorescence around the nucleus compared to empty vector cells." (PMID 40770563, 2026). "Similar results were observed in ABCC10-overexpressing cancer cells generated using CRISPR activation technology." (PMID 40770563, 2026). "In summary, we identified ABCC10 as a critical molecular site for cGAMP export in the context of cancer RT." (PMID 40770563, 2026). "In line with this, our study is the first to discover that ABCC10 functions as a cGAMP exporter in an ATP-dependent manner in cancer cells." (PMID 40770563, 2026). "We observed a marked increase in intracellular ROS in ABCC10-knockdown cancer cells, whereas ABCC10 overexpression resulted in insufficient ROS generation." (PMID 40770563, 2026). "In this study, using CRISPR-Cas9 metabolic screening, we identified ABCC10 as a critical guardian against DNA damage and a driver of immune escape, promoting cancer cell resistance to RT." (PMID 40770563, 2026). "It has been reported that lapatinib can enhance the response of cancer cells to taxanes by inhibiting ABCC10 activity, while sildenafil and vardenafil restore drug efficacy by blocking ABCC10-mediated efflux." (PMID 40573290, 2025). "This was accompanied by a downregulation of p27 and upregulation of cyclin D1 and phosphorylated pRb, suggesting that the overexpression of ABCC5 and ABCC10 facilitates cancer cell growth." (PMID 39679367, 2024). "The Cancer Genome Atlas data was analyzed to figure out the correlation between the clinical manifestation and ABCC10 expression." (PMID 36585626, 2022). "CEP effectively inhibits the drug transporter protein ABCC10 (also known as MRP7) on cancer cell membranes, thereby reversing anticancer drug resistance in cells expressing ABCC10." (PMID 36558061, 2022). "Considering our current study, EP300 emerges as a key, chromatin-bound enzyme responsible for ABCC10 overexpression in cisplatin-resistant cancer cells of different tissue origin, e.g., lung and breast." (PMID 35205642, 2022). "We found that the TSIRS was negatively correlated with cancer stemness (mRNAsi) and positively correlated with the expression of multi-drug resistance associated protein (ABCC2, ABCC3, ABCC6 and ABCC10)." (PMID 36467413, 2022). "The inhibition of this demethylase in the presence of I-CBP112 prevented the repression of ABCC1 and ABCC10 and, to a considerable extent, cancer cells’ sensitization to drugs." (PMID 34572840, 2021). "Multidrug resistance protein 7 (MRP-7, ATP-binding cassette subfamily C member 10, ABCC10) is one of the ABC transporters that allows cancer cells to become resistant to cytotoxic medicines (like paclitaxel)." (PMID 34950596, 2021).
cancer (continued). "Till now, 12 ABCC transporters have been discovered, and there are nine members (ABCC1‐6 and ABCC10‐12) also referred as “multidrug resistance protein (MRP)” due to their ability to confer multidrug resistance (MDR) in cancers." (PMID 34766143, 2021). "Among them, P-glycoprotein (P-gp/ABCB1), multidrug-resistant protein 1 (MRP1/ABCC1), breast cancer resistant protein (BCRP/ABCG2/MXR/ABCP), and multidrug-resistant protein 10 (ABCC10/MRP7) transporters frequently drive chemosensitive cancers to MDR." (PMID 28646911, 2017). "Nonetheless, several studies suggest that the overexpression of ABCC10 in cancer cells produces resistance to specific antineoplastic drugs." (PMID 25402202, 2015). "Recent data indicate that paclitaxel resistance occurs via its active efflux from cancer cells due to the expression of the ATP-binding cassette subfamily C member 10 (ABCC10), also known as multidrug resistant protein 7 (MRP7)." (PMID 25402202, 2015). "We observed that RT-treated ABCC10-overexpressing cancer cells exhibited significantly higher extracellular and lower intracellular cGAMP levels, supporting the efflux hypothesis." (PMID 40770563, 2026). "In addition, the expression levels of ABCC10 were significantly higher in radioresistant cell lines compared to their corresponding control cancer cells, suggesting that ABCC10 is a crucial determinant of RTR." (PMID 40770563, 2026). "In addition, nuclear/cytoplasmic fractionation of cancer cell lysates showed a significant reduction in cytoplasmic DNA content in RT-treated ABCC10-overexpressing cells." (PMID 40770563, 2026). "This suggests that DOX-induced ABCC10 knockdown effectively reversed RTR in the cancer cells." (PMID 40770563, 2026). "Notably, ABCC10-overexpressing cancer cells exhibited significantly increased cell viability and enhanced colony formation ability under various doses of irradiation." (PMID 40770563, 2026). "Nilotinib, a second-generation of TKI, also inhibited the efflux function of ABCB1, ABCG2, and ABCC10 in cancer cells, thereby increasing the intracellular concentrations of the chemotherapeutic agents (e.g., PTX and doxorubicin) and potentiating their cytotoxic effects both in vitro and in vivo." (PMID 35327403, 2022). "Furthermore, the expression levels of ABCC10 may serve as a potential biomarker for predicting the responsiveness of cancer patients to RT." (PMID 40770563, 2026). "To investigate whether cGAMP efflux underlies the ABCC10-mediated activation of the STING pathway, we conducted rescue experiments by either supplying ABCC10-overexpressing cancer cells with exogenous cGAMP or treating them with ctDNA to enhance endogenous cGAMP production." (PMID 40770563, 2026). "Our findings suggest that ABCC10, a novel cGAMP transporter, drives RTR in cancer cells, highlighting its potential usefulness as a biomarker for predicting RT response and as a target for therapeutic strategies to overcome resistance." (PMID 40770563, 2026). "Our results revealed that ABCC10 suppresses the STING-TBK1-IRF3 pathway, thereby facilitating cancer cell resistance to RT both in vitro and in vivo, consistent with previous publications regarding STING activation and RT efficiency." (PMID 40770563, 2026). "PD173074 is a potent inhibitor of FGFR1 and VEGFR, and it was also shown to effectively resensitize chemoresistant cancer cells overexpressing ABCB1 and ABCC10 to some chemotherapeutic agents, including paclitaxel." (PMID 41154409, 2025). "Amongst the nine primary transporters (ABCC1-6, ABCC10-12, or MRP 1-9) in the ABCC family, ABCC5 was found to transport nucleoside monophosphate analogues and produce cancer drug resistance." (PMID 35141332, 2022). "ABCC10 is a member of ABC transporter family, which play important roles in drug resistance by effluxing anticancer agents outside of cancer cells." (PMID 28051999, 2017).
cancer (continued). "Upregulation of MRP7 (ABCC10) and downregulation of MDR3 (ABCB3) suggests that the soluble factors secreted by cancer cell microenvironment can be involved in drug resistance in cancer cells." (PMID 23857432, 2013). "Our findings demonstrate that ABCC10-mediated cGAMP export functions as a negative regulator of cell-intrinsic STING signaling, thereby reducing intracellular ROS accumulation, mitigating DNA damage, and promoting cancer cell resistance to RT." (PMID 40770563, 2026). "Since many cancer cells may develop MDR via different types of ABC transporters, we examined ABCB1, ABCG2, ABCC1, and ABCC10 in this study." (PMID 27649127, 2016). "Moreover, inversely, the lack of the CoREST repressive complex at the ABCC10 promoter allows for EP300 binding and transcription enhancement in cancer cells treated with cisplatin." (PMID 35205642, 2022).
tumor (17 papers, 2012 to 2026). "In vivo, a combination of RT and nilotinib, a potential ABCC10 inhibitor, synergistically inhibited tumor growth." (PMID 40770563, 2026). "It was observed in the TCGA database that ABCC1, ABCC4, ABCC5, and ABCC10 were significantly upregulated in tumor tissues, while ABCC6 and ABCC7 were downregulated in HCC tissues." (PMID 35342392, 2022). "To extend our findings to human CRC tissues, we investigated the relationship between FOXM1 and ABCC10 expression in tumor tissues of 20 CRC patients." (PMID 28051999, 2017). "Pearson correlation analysis showed that the level of FOXM1 was correlated with that of ABCC10 in tumor tissues (R2= 0.6158, p<0." (PMID 28051999, 2017). "The i.p. dose of paclitaxel (15 mg/kg) used in this study was determined after a series of pilot experiments which indicated that it produced significant resistance in HEK293/ABCC10 tumor-xenograft model compared to the HEK293/pcDNA3.1 tumor-xenograft model." (PMID 25402202, 2015). "Importantly, the combination of the ABCC10 inhibitor nilotinib and RT exhibited a synergistic effect in inhibiting tumor growth and eliciting anti-tumor immunity." (PMID 40770563, 2026). "Moreover, we also observed elevated γ-H2A.X levels in the DOX + RT group with ABCC10 knockdown from the protein profiling of tumor tissues, indicating more pronounced DNA damage." (PMID 40770563, 2026). "Moreover, metastasis presented higher ABCC1, ABCC3 and ABCC4 expression and lower SLC22A1 and ABCC10 expression than the primary tumor." (PMID 36982681, 2023). "In vitro experiments uncovered that ABCC10 conferred tumor cells with multidrug resistance." (PMID 36585626, 2022). "Similarly, compared with PC9/GR-shMock group, ABCC10 knockdown significantly decreased the average TV and tumor weight by 19% (365.8 ± 96.5 mm3 vs. 452.1 ± 86.3 mm3) and 12% (1.5 ± 0.4 g vs. 1.7 ± 0.5 g) in PC9/GR-shABCC10 group, respectively." (PMID 30515095, 2018). "Considering the gefitinib concentration in NSCLC tumor tissues is more than 40-fold higher than plasma levels, we speculate that ABCC10 may play a more important role than ABCG2 in acquired resistance to gefitinib in vivo." (PMID 30515095, 2018). "And as expected, ABCC10 also enhanced tumor growth in gefitinib-treated NSCLC xenograft models." (PMID 30515095, 2018). "Furthermore, we demonstrate that NVP-BHG712 enhanced paclitaxel-mediated inhibition of the growth of ABCC10-expressing tumor in a tumor xenograft mouse model in vivo and report the tumor and plasma concentration of paclitaxel in mice administered with paclitaxel and NVP-BHG712." (PMID 25402202, 2015). "The results showed that the tumor biopsy presented high ABCC6 and ABCC10 expression, and metastasis presented high ABCB1 expression when metastasis was present at diagnosis." (PMID 36982681, 2023). "Four other ABC transporters showed this pattern, with elevation in the MDR tumor at least two-fold greater than in the control sample, and reduced by metformin (ABCA3, ABCC10, ABCG1, and ABCB3)." (PMID 36077749, 2022). "To explore a strategy to block ABCC10 in CRC cells, we paid a special interest in the endoplasmic reticulum stress (ERS) / unfolded protein response (UPR) that plays a dual role in tumor development." (PMID 36585626, 2022).
infection (1 paper, 2015). The state of being infected such as from the introduction of a foreign agent such as serum, vaccine, antigenic substance or organism. "It is thus likely that modulating gene expression of ABCC10 (downregulated in all nine datasets at 12 h and upregulated in all six datasets at 24 h post-infection) might be interfering with the transport of molecules across HIV-1-infected T-cells." (PMID 26426037, 2015).
ABCC10 also shares sentences with these, for which no sentence is quoted: esophageal carcinoma (2 papers); epilepsy (1); head and neck cancer (1); hyperlipidemia (1); liver cancer (1); multiple myeloma (1); myocardial infarction (1); oral squamous cell carcinoma (1); osteosarcoma (1); ovarian carcinoma (1); ovarian tumours (1); prostate carcinoma (1); retinoblastoma (1); Tinnitus (1).